PPP1R1B (protein phosphatase 1 regulatory inhibitor subunit 1B)
Description:
Inhibitor of protein-phosphatase 1.
Synonyms: DARPP32; DARPP-32; FLJ20940
Tractability: PROTAC: its protein half-life has been measured.
Gene: Protein-coding gene on chromosome 17 (39,626,740 to 39,636,626, forward strand). Ensembl gene ENSG00000131771.
Subcellular location: Cytoplasm
Pathways (Reactome):
Signal Transduction: DARPP-32 events
Gene Ontology:
Molecular function: protein binding; protein phosphatase inhibitor activity; cAMP-dependent protein kinase inhibitor activity; protein kinase inhibitor activity; protein phosphatase regulator activity
Biological process: intracellular signal transduction; signal transduction
Cellular component: cytoplasm; cytosol; neuronal cell body; nucleus
Genetic constraint (gnomAD): Loss-of-function variants: 10 observed, 28.71 expected, observed/expected ratio (o/e) 0.35, 90% interval 0.21 to 0.59. The upper end of that interval is the gene's LOEUF score, 0.59, which puts it in group 2 of 6, group 1 being the genes least tolerant of losing a copy. Missense variants: 234 observed, 258 expected, observed/expected ratio (o/e) 0.91, 90% interval 0.81 to 1.01. Synonymous variants: 102 observed, 98.8 expected, observed/expected ratio (o/e) 1.03, 90% interval 0.88 to 1.22.
Homologues: Orthologues: chimpanzee PPP1R1B (99% identical), macaque PPP1R1B (95% identical), pig PPP1R1B (93% identical), dog PPP1R1B (91% identical), guinea pig PPP1R1B (83% identical), mouse Ppp1r1b (83% identical), rabbit PPP1R1B (70% identical), zebrafish ppp1r1b (34% identical), tropical clawed frog ppp1r1b (27% identical). Paralogues in human: PPP1R1A (25% identical), PPP1R1C (21% identical).
Diseases named in the same sentence as PPP1R1B in open-access papers:
PPP1R1B is named in the same sentence as 94 diseases in open-access papers, as found by Europe PMC text mining. Sharing a sentence is not in itself a finding about the gene and the disease. The quoted sentences say what the papers report.
schizophrenia (30 papers, 2008 to 2024). A major psychotic disorder characterized by abnormalities in the perception or expression of reality. "Among candidate genes, Ppp1r1b (encoding Darpp32) was selected based on its significance for normal brain function and its role in psychiatric disorders, such as schizophrenia and anxiety." (PMID 31253786, 2019). "Genetic and immunoblot studies showed an association of PPP1R1B with altered PFC DARPP-32 protein levels in schizophrenia and bipolar disorder, two conditions for which DA dysfunction is evident and which exhibit comorbidity with autism." (PMID 22559203, 2012). "PPP1R1B acts as an integrator of dopaminergic and glutamatergic signaling, and elevated levels of its truncated isoform have been observed in schizophrenia, bipolar disorders, major depression, and poor cognitive functioning." (PMID 31557158, 2019). "A meta-analysis found that putative schizophrenia risk variants in genes including ZNF804A, PRODH, DISC1 and PPP1R1B, reduced functional connectivity, while the genetic changes examined had no overall effect on structural connectivity." (PMID 27450778, 2016). "Our analysis showed that both disorders share three common DETs, namely Rgs4, Ppp1r1b and Chgb, whose expression is downregulated in humans with Huntington's disease or schizophrenia." (PMID 19799774, 2009). "We previously have shown that polymorphisms in the PPP1R1B and in AKT1 linked to increased striatal frontal connectivity and decreased striatal volume were associated with genetic risk for schizophrenia." (PMID 18989458, 2008). "For example, it was shown that specific polymorphisms in PPP1R1B, the gene encoding DARPP-32 in the human brain, were associated with the risk for schizophrenia and may predict autism susceptibility." (PMID 30173406, 2019).
gastric cancer (21 papers, 2004 to 2025). A primary or metastatic malignant neoplasm involving the stomach. "In gastric cancer, it has been found that NF-κB transcriptionally upregulates PPP1R1B gene expression in vitro and in vivo models." (PMID 38308500, 2024). "Some studies demonstrated that PPP1R1B was overexpressed in diverse human cancers, including colon, breast, and gastric cancer." (PMID 36445321, 2022). "A PPP1R1B-STARD3 fusion transcript has also been identified in gastric cancer, that increases in vitro cell proliferation through the phosphatidylinositol-3-kinase (PI3K)/AKT pathway." (PMID 31740718, 2019). "It has been reported that the PPP1R1B-STARD3-TCAP-PNMT-PERLD1-ERBB2-MGC14832-GRB7 locus at chromosome 17ql2 is frequently amplified in gastric cancer and breast cancer." (PMID 30567531, 2018). "Furthermore, the PPP1R1B-STARD3 fusion transcript in human gastric cancer increases colony formation through the activation of phosphatidylinosil-3-kinase and AKT signaling." (PMID 26360582, 2015). "In addition to tumor suppressors, we also observed several candidate oncogenes to be expressed at lower levels in EBVaGCs including 4 (CDH17, CDX1, ETV4, and PPP1R1B) known to be over expressed in gastric carcinoma and gastrointestinal cancers." (PMID 23671415, 2013). "For example; in gastric cancers the frequently amplified 17q12-q21 region contains genes such as ERBB2, GRB7, JUP, PERLD1, PNMT, PPP1R1B, STARD3, and TOP2A." (PMID 20187983, 2010). "Both of these genes are part of the PPP1R1B-STARD3-TCAP-PNMT-PERLD1-ERBB2-MGC14832-GRB7 locus at the 17q12 region, which has previously been reported to be gained and overexpressed in breast and gastric cancers." (PMID 20187983, 2010).
breast carcinoma (20 papers, 2006 to 2025). "The transcripts identified through RNA-Seq of DARPP-32 knockdown T47D breast cancer cells were compared with those identified as associated with PPP1R1B expression in the METABRIC patient cohort." (PMID 38036593, 2023). "In addition, this study demonstrated that PPP1R1B was significantly associated with breast cancer prognosis." (PMID 37626402, 2023). "The significant differentially expressed transcripts identified through RNA-Seq of DARPP-32 knockdown T47D breast cancer cells were compared with those identified as associated with PPP1R1B expression in the METABRIC patient cohort using ANN analysis to find common genes." (PMID 38036593, 2023). "In addition to protein expression, we sought to assess PPP1R1B mRNA expression in a large, well-annotated series of breast cancer patients, including artificial neural network analysis to identify genes associated with PPP1R1B expression." (PMID 31740718, 2019). "RNA-sequencing (RNA-Seq) of trastuzumab-resistant breast cancer cells further identified PPP1R1B upregulation." (PMID 38036593, 2023). "Tissue immunofluorescence staining was performed to investigate the distribution of these markers such as En_CXCR4, En_PPP1R1B, and En_S100A9 in breast cancer tissues and the relationship with the position distribution of blood vessels." (PMID 37626402, 2023). "By integrating scRNA-seq, we constructed a single-cell landscape from eight breast cancer tissues and found that PPP1R1B is specifically expressed in BRCA_PPP1R1B and En_PPP1R1B." (PMID 37626402, 2023). "This study showed sEVs derived from breast cancer malignant cells promote blood vessel formation by activating endothelial cells through the transfer of PPP1R1B." (PMID 37626402, 2023). "Specifically, AGR3 promotes tamoxifen resistance in breast cancer, SRGN is a key molecule in mediating chemoresistance and stemness in breast cancer cells, and PPP1R1B is involved in resistance of breast cancer cells to trastuzumab." (PMID 37626402, 2023). "Decreased tumor growth in Ppp1r1b knockout mice also suggests that t-Darpp plays a direct role, predominant to Darpp-32, in mammary tumor development." (PMID 25128420, 2014). "And PPP1R1B may also regulate pro-oncogenic signal transduction pathways to promote chemoresistance and increase gastric and breast cancer cell viability." (PMID 36445321, 2022). "The data from the Ppp1r1b knockout tumor mice suggest that the Ppp1r1b gene products, t-Darpp in particular, could have a direct role in mammary tumor development in MMTV-PyMT mice." (PMID 25128420, 2014). "En_CXCR4, En_S100A9, and En_PPP1R1B were specifically highly expressed in the angiogenic group, suggesting that these marker genes may be new targets for anti-angiogenic therapy and forebode breast cancer prognosis in the future." (PMID 37626402, 2023). "In addition, BRCA_PPP1R1B was also found in a high proportion of angiogenic breast cancer." (PMID 37626402, 2023).
Huntington disease (12 papers, 2009 to 2025). Huntington disease (HD) is a rare neurodegenerative disorder of the central nervous system characterized by unwanted choreatic movements, behavioral and psychiatric disturbances and dementia. "In a Huntington’s disease (HD) mouse model, treatment with memantine or targeting the NMDAR/TRPM4 complex with FP802 restored gene expression, notably Inhba, Homer1 and Bdnf, and attenuated the decrease of the HD disease marker Ppp1r1b (DARPP-32)." (PMID 41339520, 2025).
depression (9 papers, 2015 to 2022). "The expressions of Gfap and Uqcrh were significantly upregulated, whereas Rhog, Gnai2, and Ppp1r1b were downregulated in the depression-susceptible group when contrasted to the control group." (PMID 33627638, 2021). "The results showed that Gfap, Rhog, Gnai2, Ppp1r1b, and Uqcrh were specifically dysregulated in the prefrontal cortex of the depression-susceptible group, while Tubb6, Urod, Cul1, Spred1, and Gpcpd1 were specifically dysregulated in the anxiety-susceptible group." (PMID 33627638, 2021). "In contrast, physical exercise may rebalance DA signaling after sustained L-DOPA treatment (by reducing PPP1R1B activation), attenuates depression-like behavior by decreasing the expression of neuropeptides and activates the endocannabinoid system." (PMID 29019056, 2018).
pancreatic cancer (9 papers, 2021 to 2025). "PPP1R1B encodes protein phosphatase one regulatory inhibitor subunit 1B and the knockdown of PPP1R1B impaired the ability of lung metastases in pancreatic cancer cells in mice." (PMID 34566519, 2021). "Upregulation of Ppp1r1b is associated with gastric, breast, colon, esophageal, lung, and prostate cancers, and correlates to worse survival outcomes in pancreatic cancer." (PMID 40970443, 2025). "PPP1R1B can modulate downstream signaling of various kinases in pancreatic cancer by regulating proteins phosphatase 1 activity, which in turn regulates the activity of many phosphorylated proteins." (PMID 35935941, 2022). "PPP1R1B, SMARCA4, and TGFB1 have well-described roles in the pathogenesis of pancreatic cancer." (PMID 34009124, 2021).
cocaine addiction (4 papers, 2020 to 2022). "Among up- and downregulated genes from the pathway hsa05030:cocaine addiction are genes JUN, GNAS, BDFN, and CDK5R1 (upregulated), and FOSB, NFKB1, CREB1 and PPP1R1B (downregulated)." (PMID 34947877, 2021).
colorectal cancer (4 papers, 2019 to 2023). A primary or metastatic malignant neoplasm that affects the colon or rectum. "Long noncoding RNA KCNQ1OT1 upregulates the methotrexate resistance of colorectal cancer cells by inhibiting miR-760/PPP1R1B." (PMID 36726491, 2023). "We aimed to explore the mechanism of the KCNQ1OT1/miR‐760/PPP1R1B axis acting to regulate methotrexate (MTX) resistance of colorectal cancer (CRC)." (PMID 30997746, 2019).
autism (3 papers, 2012 to 2021). Persistent deficits in social interaction and communication and interaction as well as a markedly restricted repertoire of activity and interest as well as repetitive patterns of behavior. "Based on our findings in this study and our previous findings, single-gene analyses showed evidence for association of DRD1DRD2 and PPP1R1B with autism in male-only affected sib-pair families." (PMID 22559203, 2012). "Our findings support a role for the DRD2 and PPP1R1B genes in conferring risk for autism in families with only affected males and show an additive effect of these genes towards prediction of affected status in our families." (PMID 22559203, 2012). "The QTDT results support an association of the DRD2 and PPP1R1B loci with autism." (PMID 22559203, 2012). "Following our findings with the DRD1 gene, and as part of our investigation to determine whether other DA-related genes are significant factors in the etiology of ASDs, we found evidence for association of the DRD2 and PPP1R1B genes with autism in affected males from multiple-incidence families." (PMID 22559203, 2012). "We also found that 97% of individuals from our comparison cohort and 13% of individuals with autism were correctly classified while 72% of control individuals and 64% of affected individuals were predicted correctly using a weighted additive combination of DRD2 and PPP1R1B genotypes." (PMID 22559203, 2012).
prostate carcinoma (3 papers, 2017 to 2025). A carcinoma that arises from epithelial cells of the prostate gland. "t‐Darpp (truncated isoform of dopamine‐ and cAMP‐regulated phosphoprotein) is a protein encoded by the PPP1R1B gene and is expressed in breast, colon, esophageal, gastric, and prostate cancers, as well as in normal adult brain striatal cells." (PMID 28904862, 2017).
substance abuse (3 papers, 2015 to 2022). The use of a drug for a reason other than which it was intended or in a manner or in quantities other than directed. "DA- and cAMP-regulated neuronal phosphoprotein PPP1R1B and vesicular glutamate transporter SLC17A7 may be molecular targets for the treatment of substance abuse." (PMID 36362437, 2022). "Gene expression networks consisted of recognized substrates for addiction, such as the dopamine- and cAMP-regulated neuronal phosphoprotein PPP1R1B/DARPP-32 and the vesicular glutamate transporter SLC17A7/VGLUT1 as well as potentially novel molecular targets for substance abuse." (PMID 26041984, 2015).
cardiomyopathy (2 papers, 2020 to 2023). A disease of the heart muscle or myocardium proper. "The enrichments with myogenesis, muscle contractions, and cardiomyopathy in the interacted genes reinforce the essential role of Ppp1r1b-lncRNA in myogenic differentiation." (PMID 38132125, 2023). "(iii) Examining the translational value of Ppp1r1b-lncRNA manipulation requires temporal and tissue specific in vivo delivery of Ppp1r1b-lncRNA in disease models of muscular dystrophy, cardiomyopathy, and congenital heart disease." (PMID 31953255, 2020).
colon cancer (2 papers, 2019 to 2024). "PPP1R1B, together with its downstream proteins, is overexpressed in diverse adenocarcinomas, including colon cancer." (PMID 30997746, 2019).
acute lymphoblastic leukemia (1 paper, 2024). Leukemia with an acute onset, characterized by the presence of lymphoblasts in the bone marrow and the peripheral blood. "To gain further insight into the exclusivity of the PPP1R1B::STARD3 fusion, we analyzed two RNA-seq data profiles (including GSE115525 and PRJNA589314) for B-cell acute lymphoblastic leukemia (B-ALL) samples." (PMID 38835078, 2024).
alcoholism (1 paper, 2022). "Interestingly, the GO term “alcoholism” was enriched in genes associated with the “CGI-free intergenic UMR” category, including Shc3, Shc4, Araf, Fosb, Hdac11, Adcy5, Creb3l2, Gnai2, Grin2d, and Ppp1r1b." (PMID 35205351, 2022).
amyotrophic lateral sclerosis (1 paper, 2009). Amyotrophic lateral sclerosis (ALS) is a neurodegenerative disease characterized by progressive muscular paralysis reflecting degeneration of motor neurons in the primary motor cortex, corticospinal tracts, brainstem and spinal cord. "In this case, 4 out of 5 genes from FOSB pathway were mapped to the 2 diseases: CDK5 and GRIA2 to amyotrophic lateral sclerosis and, FOSB and PPP1R1B to drug-induced dyskinesia." (PMID 19194489, 2009).
anxiety disorder (1 paper, 2019). A category of psychiatric disorders which are characterized by anxious feelings or fear often accompanied by physical symptoms associated with anxiety. "We selected two of these proteins, PPP1R1B and CYCS (cytochrome c somatic), which have been previously associated with psychiatric disorders, including anxiety disorders, for validation by Western blot analysis." (PMID 31557158, 2019).
colitis (1 paper, 2025). Inflammation of the colon. "While the impact of Ppp1r1b cleavage in the gut is unknown, it is possible that legumain‐mediated cleavage of Pppr1r1b contributes to colitis pathogenesis." (PMID 40970443, 2025).
congenital heart disease (1 paper, 2020). A heart disease that is present at birth. "Our results may facilitate our understanding of the function of Ppp1r1b-lncRNA and provide us with a promising therapeutic target for congenital heart disease and skeletal myopathy." (PMID 31953255, 2020).
glycogenosis (1 paper, 2023). "PPP1R1B suppresses protein phosphatase 1 and induces glycogenosis." (PMID 37628732, 2023).
head and neck cancer (1 paper, 2024). A primary or metastatic malignant neoplasm affecting the head and neck. "In head and neck cancer, there exist 37 genes such as PPP1R1B and CDC6 with significant association between mRNA abundance and the interaction of the sex and CNAs." (PMID 39011274, 2024).
hepatoma (1 paper, 2023). "Moreover, the expression of PPP1R1B, TMEM45B, AFP, and ENPEP followed the same pattern in vitro using human hepatoma (HEPG2) and mouse liver 12 (AML12) cell lines incubated with squalene, indicating a direct effect of squalene on these expressions." (PMID 37628732, 2023).
hyperlipidemia (1 paper, 2022). "Moreover, neuropathy, ketoacidosis and hyperlipidemia were associated with significant upregulations in expression of PPP1R1B, TCEB3C and OR11H12 as shown in Boxplots 8E, 8G and 8J, respectively." (PMID 36175575, 2022).
nicotine addiction (1 paper, 2022). "In the network of genes annotated to the cocaine pathway (also in the nicotine addiction pathway), ADCY5, DRD1, DRD2, PPP1R1B, and protein kinase C β (PRKCB) were over-expressed in Control nursed males relative to all pig groups with exception of Control weaned females." (PMID 35627199, 2022).
cancer (32 papers, 2004 to 2025). A tumor composed of atypical neoplastic, often pleomorphic cells that invade other tissues. "In all the three GC datasets, the positive regulation of PPP1R1B by XBP1 was increased from normal to cancer, and the negative regulation of FKBP11 by XBP1 was strengthened." (PMID 29745833, 2018). "Overexpression of PPP1R1B::STARD3 may increase cancer cell proliferation and tumorigenesis by activating the PI3K/AKT pathway." (PMID 38835078, 2024). "Furthermore, former studies on PPP1R1B have focused more on neurological and psychiatric disorders than on cancer, especially CRC, offering us a novel research direction." (PMID 30997746, 2019). "In addition, the role of the KCNQ1OT1/miR‐760/PPP1R1B axis should be investigated in other mechanisms of cancer cells resistance to chemotherapeutics." (PMID 30997746, 2019). "A number of cancer-related genes are located in these two RARs: NUPR1, MVP, MAPK3, FUS, and PYCARD are located in RAR-G12 while ERBB2, GRB7, and PPP1R1B are located in RAR-G13." (PMID 22938721, 2012). "PPP1R1B::STARD3 may be considered a candidate for targeted therapies of the cholesterol metabolic and the PI3K/AKT signaling pathways involved in cancer development and progression." (PMID 38835078, 2024). "However, the role of genes such as PNMT, TCAP, and PPP1R1B in BC and other cancers is still not well defined, requiring further research to understand their potential as biomarkers or therapeutic targets." (PMID 40136626, 2025).